DRD2 (dopamine receptor D2)
Diseases named in the same sentence as DRD2 in open-access papers (continued):
Sharing a sentence is not in itself a finding about the gene and the disease.
opioid use disorder (5 papers, 2015 to 2023). A substance-related disorder that involves the recurring use of opioids despite negative consequences. "The DRD2 rs1076560 SNP was found to be associated with opioid use disorder in the two populations examined in this subsequent study (EA: p = 0.02, AA: p = 0.03), but not cocaine use (EA: p = 0.23, AA: p = 0.19)." (PMID 29881439, 2018). "The aim of this study was to investigate the effect of brain-derived neurotrophic factor (BDNF) and dopamine receptor D2 (DRD2) polymorphisms on continued opioid use among patients on methadone treatment for opioid use disorder." (PMID 26437921, 2015). "BDNF 196G>A (rs6265) and DRD2-241A>G (rs1799978) genetic variants were examined in patients with opioid use disorder who were recruited from methadone treatment clinics across Southern Ontario, Canada." (PMID 26437921, 2015). "Variation in addiction-related genes (such as BDNF and DRD2) due to polymorphisms in the genetic sequence may confer susceptibility to continued opioid use while on methadone treatment for opioid use disorder." (PMID 26437921, 2015). "A promising target polymorphism, DRD2-241A>G (rs1799978), is of particular interest, as it has shown preliminary evidence for an association with opioid use disorder and methadone dose in a sample of 85 German drug users admitted to an outpatient methadone treatment center." (PMID 26437921, 2015). "Among them, a recent study on multivariate GWAS has reported rs6589386 on DRD2 as the most significant signal associated with the addiction risk factor, a general genetic factor underlying problematic alcohol use, tobacco use, cannabis use disorder and opioid use disorder." (PMID 37147289, 2023). "Dopamine receptor D2 (DRD2) polymorphism is associated with addictive behavior; DRD2 gene Taql RLFP A (rs1800497) was studied in patients with an opioid use disorder versus control." (PMID 33987515, 2020). "Similarly, the dopamine receptor D2 (DRD2) gene plays a major role in opioid use disorders because of its involvement in the reward–dependence pathway." (PMID 26437921, 2015).
ovarian carcinoma (5 papers, 2020 to 2025). A malignant neoplasm originating from the surface ovarian epithelium. "Given ovarian cancer has >60% DRD2 surface expression it was felt that ONC201 would be an excellent candidate agent to study in this setting." (PMID 33932119, 2021).
Tics (5 papers, 2018 to 2024). Repeated, individually recognizable, intermittent movements or movement fragments that are almost always briefly suppressible and are usually associated with awareness of an urge to perform the movement. "Moreover, excessive release of striatal dopamine appears to be the reason for the dysfunction of BGCTC in tic patients, and dopamine receptor D2 antagonists that can inhibit dopamine-induced effects represent the most efficacious pharmacotherapy of tics in clinic." (PMID 37090922, 2023).
acute myeloid leukemia (4 papers, 2016 to 2021). Acute myeloid leukemia (AML) is a group of neoplasms arising from precursor cells committed to the myeloid cell-line differentiation. "establish reliable assays that predict clinical responsiveness to a dopamine receptor 2 (DRD2) antagonist using patient samples from a Phase I clinical study of acute myeloid leukemia." (PMID 33665638, 2021). "Finally, thioridazine, an anti-psychotic drug, was repurposed to selectively inhibit the development of acute myeloid leukemia derived from their CSC through antagonizing DRD2." (PMID 27283899, 2016). "A phase I trial has been conducted on acute myeloid leukemia (AML) patients to evaluate thioridazine in combination with cytarabine and preliminary results suggest that DRD2 represents a potential therapeutic target for AML." (PMID 31993373, 2019).
behavioral addiction (4 papers, 2014 to 2024). "It is associated with the differential availability of the dopamine receptor D2 and has sparked interest in genetic research on behavioral addictions." (PMID 38397159, 2024). "However, genetic polymorphisms that alter the availability and expression of the dopamine receptor D2 are associated with both substance and behavioral addictions." (PMID 38397159, 2024). "A backward stepwise regression analysis identified age, male sex, dopamine replacement therapy and ADRA2C, DRD2, DDC, HTR2A and OPRK1 genotypes as significant predictors of behavioral addiction / impulse control disorders." (PMID 33324875, 2019).
cognitive decline (4 papers, 2021 to 2025). "There is little evidence for impact of genetic polymorphisms in dopamine receptors on cognitive course in PD beyond a single, small study reporting an association between DRD2 and long‐term cognitive decline." (PMID 37332638, 2023). "The authors found that the T/T allele in rs6277 SNP in DRD2 was associated with an increased risk of cognitive decline in PD." (PMID 33917417, 2021). "Specifically, this genotype significantly increased the hazard for developing cognitive decline 3.2 times in comparison with PD patients with other DRD2 genotypes, and determined poorer performances in episodic memory and attention." (PMID 33917417, 2021). "Other side-effects such as cognitive decline, visual hallucinations and daytime sleepiness have been implicated in various polymorphisms of the COMT, DRD2, DRD3, HOMER1 and BDNF genes, but lack consistency in the results to consider current clinical implementations." (PMID 34281267, 2021).
colitis (4 papers, 2020 to 2025). Inflammation of the colon. "We find that mice harbouring Drd2-deficient T-cells developed more severe colitis induced by dextran sodium sulphate." (PMID 41155360, 2025). "The subsequent comprehensive in silico analysis revealed the ability of TM to bind to the active sites of key colitis-associated regulators, including Akt1, Src, STAT3 and dopamine receptor D2." (PMID 32455822, 2020).
delirium (4 papers, 2014 to 2023). A disorder characterized by confusion; inattentiveness; disorientation; illusions; hallucinations; agitation; and in some instances autonomic nervous system overactivity. "A further meta-analysis concluded that the homozygous AA genotype of rs393795 in the SLC6A3 gene was more frequent in patients without delirium, and the homozygous GG genotype of rs6276 in the DRD2 gene was more frequent in patients without delirium after adjustment for cognitive impairment." (PMID 24795632, 2014).
dementia (4 papers, 2018 to 2024). Loss of intellectual abilities interfering with an individual's social and occupational functions. "Genotype and allele frequencies of DRD2 (rs1076560) variants were associated with risk of dementia (p = 0.001) and resulted in parts II and III of the UPDRS scale (p = 0.001)." (PMID 35044623, 2022). "Presented results demonstrate that the CC genotype of DRD2 rs228365 was associated with dementia compared to the AA genotype." (PMID 35044623, 2022). "According to our results, the A/C genotype in rs1076560 polymorphism of the DRD2 gene is associated with dementia." (PMID 35044623, 2022). "Genotype and allele frequencies of DRD2 (rs2283265) variants were associated with risk of dementia (p = 0.001) and resulted in parts II and III of the UPDRS scale (p = 0.001)." (PMID 35044623, 2022). "Additionally, brain DRD2 is reduced as we age, and aging-induced dementia is associated with an acceleration in DRD2 reduction." (PMID 38765881, 2024). "We examined the effect of the Taq1A polymorphism of the DRD2/ANKK1 gene on caudate structure and cognitive performance in older adults without dementia." (PMID 29564530, 2018). "To address these possibilities, we explored the interaction between the DRD2/ANKK1 Taq1A polymorphism and age on caudate volume in a large sample of older adults without dementia (n = 387)." (PMID 29564530, 2018).
dyslexia (4 papers, 2014 to 2025). A learning disorder characterized by an impairment in processing written words. "In DRD2 gene, we genotyped 11 Tag SNPs and found nominal association (P < 0.05) of five SNPs with dyslexia in our cohort." (PMID 25178928, 2014). "Here, we aimed to examine the association between dyslexia and dopaminergic genes (dopamine receptor DRD2 and dopamine transporter SLC6A3)." (PMID 25178928, 2014). "In conclusion, we found significant association between one SNP marker within DRD2 and development dyslexia in a large unrelated Chinese cohort." (PMID 25178928, 2014). "In DRD2 gene, using a recessive model, we demonstrated that rs1079727 was significantly associated with dyslexia with the allele C as a risk factor after Bonferonni correction." (PMID 25178928, 2014). "Its pathogenesis may be associated with the overlap of the dyslexia gene DRD2, although further investigation is required to confirm this relationship." (PMID 39020327, 2024). "Our finding supports the involvement of DRD2 polymorphisms in the development of dyslexia." (PMID 25178928, 2014). "Among the top 20 genes with the highest priority DRD2, DRD4, CNTNAP2 and GRIN2B are mentioned in the literature as directly linked with the comorbidity of ADHD and dyslexia." (PMID 37667328, 2023). "Hence, it is conceivable that changes in the DRD2 genotype may eventually impair the working memory of dyslexia children in our study." (PMID 25178928, 2014). "We proposed that stuttering candidate genes, DRD2 and SLC6A3, might be associated with dyslexia." (PMID 25178928, 2014). "Based on existing findings, dopaminergic genes DRD2 and SLC6A3 are believed to be candidate genes for dyslexia." (PMID 25178928, 2014).
generalized anxiety disorder (4 papers, 2019 to 2025). An anxiety disorder characterized by excessive and difficult-to-control worry about a number of life situations. "Specifically, the ANKK1-DRD2 genes are linked to comorbid MDD and Generalized anxiety disorder (GAD) in adults with ADHD, whereas the NCAM1 and DRD2 genes independently contribute to the susceptibility to MDD in these patients." (PMID 40547117, 2025). "Similar to DRD2, NRXN1 interacts with a range of psychiatric medications such as duloxetine, which is used for MD, generalized anxiety disorder (GAD), fibromyalgia, chronic musculoskeletal pain, and osteoarthritis of the knee." (PMID 34603368, 2021).
inflammatory bowel disease (4 papers, 2018 to 2025). A spectrum of small and large bowel inflammatory diseases of unknown etiology. "Indeed, a genetic polymorphism of DRD2 gene, which results in decreased receptor expression, has been reported as a risk factor for inflammatory bowel diseases." (PMID 30042660, 2018). "In recent years, both DRD1 and DRD2 agonists have been shown to prevent the development of vascular hyperpermeability in animal models of ALI 40, 42, ovarian hyperstimulation syndrome 48, and inflammatory bowel disease." (PMID 33456556, 2021).
intracerebral hemorrhage (4 papers, 2015 to 2021). A cerebrovascular disorder characterized by bleeding into one or both cerebral hemispheres including the basal ganglia and the cerebral cortex. "Recently, studies have demonstrated that activation of the astrocytic dopamine D2 receptor (DRD2) suppressed neuroinflammation in intracerebral hemorrhage and 1-methyl-4-phenyl-1,2,3,6-tetrahydropyridine (MPTP)-induced neurotoxicity." (PMID 27724964, 2016).
ovarian hyperstimulation syndrome (4 papers, 2021 to 2026). A complication of ovulation induction in infertility treatment. "Decreased Drd2 expression in the theca was related to an increased vascularization in the theca of PCOS follicles, and overproduction of VEGF may lead to ovarian hyperstimulation syndrome." (PMID 34306142, 2021).
pheochromocytoma (4 papers, 2009 to 2021). "DRD2 mRNA levels show an early and transient reduction in the striatum after hypoxia-ischemia in newborn rats, and attenuation of DRD2 mediated inhibition of calcium influx in pheochromocytoma cells has been reported in hypoxia." (PMID 19653907, 2009). "On tumour cells of 30/63 pheochromocytomas, DRD2 protein was highly expressed." (PMID 31478179, 2020). "This unexpected discovery on the DRD2 being a direct-binding target for ONC201, has also led to the design and launch of a clinical trial of ONC201 in pheochromocytomas, owing to high levels of DRD2 expression in this rare tumor type (trial identifier: NCT03034200)." (PMID 31745082, 2019).
sexual dysfunction (4 papers, 2012 to 2025). Disturbances in sexual desire and the psychophysiologic changes that characterize the sexual response cycle and cause marked distress and interpersonal difficulty. "The functional −141Ins/Del promoter region polymorphism of DRD2 was remarkably correlated with sexual dysfunction." (PMID 32161689, 2020).
Tremor (4 papers, 2021 to 2024). An unintentional, oscillating to-and-fro muscle movement about a joint axis. "Patients with HTR2A rs6313 more often complained of tremor.DRD2 rs1800497 was significantly associated with tremor." (PMID 35745668, 2022).
triple-negative breast carcinoma (4 papers, 2019 to 2021). An invasive breast carcinoma which is negative for expression of estrogen receptor (ER), progesterone receptor (PR), and human epidermal growth factor receptor 2 (HER2). "We previously showed that 1 μM thioridazine inhibits self-renewal in some triple-negative breast cancer cell lines through DRD2 inhibition." (PMID 31822725, 2019). "Previous work from our group demonstrated that 5–10 μM thioridazine causes cell cycle arrest in 6 triple-negative breast cancer cell lines tested, but that this is independent of DRD2." (PMID 31822725, 2019). "Additionally, our study showed that thioridazine inhibits self-renewal of certain triple-negative breast cancer cell lines via DRD2 inhibition." (PMID 31822725, 2019). "In some, but not all, triple-negative breast cancer cells, in which dopamine receptor 2 (DRD2) promotes self-renewal via a STAT3- and IL-6-dependent mechanism, thioridazine inhibits self-renewal through DRD2 inhibition." (PMID 34073600, 2021). "The authors demonstrate that STAT3/IL6 stimulation governed the DRD2-induced stem cell self-renewal in triple-negative breast cancers, while the induction of cell-cycle arrest at G1 and reduction in cell proliferation and viability were reported to be independent of DRD2." (PMID 34422720, 2021).
acute pancreatitis (3 papers, 2022 to 2023). An acute inflammatory process that leads to necrosis of the pancreatic parenchyma. "Another work addressed that DRD2 activation also exerts a protective effect against acute pancreatitis and reduces systemic inflammation by inhibiting M1 macrophages through the bone marrow-specific D2DR signaling control." (PMID 36278007, 2022). "In addition, Han and colleagues demonstrated that DRD2 activation inhibits the inflammatory response in acute pancreatitis through the PP2A-dependent Akt/NF-κB pathway." (PMID 35359858, 2022).
alexithymia (3 papers, 2018 to 2024). An agnosia that is a deficiency in understanding, processing, or describing emotions. "In particular, the A1+ allele of the DRD2/ANKK1 TaqI A SNP (rs1800497) is related to alexithymia, and prior emotional abuse leads to a higher risk of alcohol problems." (PMID 39202385, 2024). "First, the A1+ allele of the DRD2/ANKK1 gene is statistically linked to alexithymia." (PMID 39202385, 2024). "The main candidate genes associated with alexithymia are from the serotoninergic pathway (SLC6A4, HTR1A and HTR2A) and neurotransmitter metabolism (DRD2/ANKK1, COMT, BDNF, and OXTR)." (PMID 39202385, 2024).
astrocytoma (3 papers, 2009 to 2021). "Receptor overexpression in rare cancers included 5-HTR1B in nasopharyngeal carcinoma (17%), DRD1 in ependymoma (30%) and synovial sarcoma (21%), and DRD2 in astrocytoma (13%)." (PMID 31478179, 2020). "DRD2 was most frequently overexpressed in adrenal neuroblastoma (24 out of 96 (25%) samples) and astrocytoma (3 out of 24 (13%) samples)." (PMID 31478179, 2020). "The levels of DRD2 are also higher in the GBM group than in the grade II and III astrocytoma groups and the non-tumor group." (PMID 34503167, 2021).
brain injury (3 papers, 2017 to 2021). Acute and chronic (see also brain INJURIES, CHRONIC) injuries to the brain, including the cerebral hemispheres, CEREBELLUM, and brain STEM. "Specifically, studies could be done regarding the COMT and DRD2 as potential candidate genes in relation to concussion, as previous studies have linked these genes to significant anomalies in cognitive function and ERP components." (PMID 29910309, 2018). "The genes of particular interest for their potential effect on event-related potentials are Apolipoprotein E, Catechol-O-methyltransferase, and Dopamine Receptor D2, as they have been previously suggested to influence concussion susceptibility and cognitive function." (PMID 29910309, 2018). "Further examination of the influence of DRD2 as a candidate gene exploring relationships between executive function and concussion history, although much further work would be needed." (PMID 29910309, 2018). "In this context it is of note that increased mRNA levels of DRD1 and DRD2 in the intestinal mucosa after traumatic brain injury correlated with an impaired intestinal mucosal barrier function." (PMID 28057070, 2017).
bulimia nervosa (3 papers, 2014 to 2022). A disorder characterized by recurrent episodes of binge-eating over which the individual feels a lack of control; these episodes of binge-eating are followed by recurrent compensatory behavior to prevent weight gain, usually self-induced vomiting. "Anomalies in DNA methylation in the promoter regions of alpha synuclein, the dopamine transporter, and the dopamine 2 receptor D2 (DRD2) have been reported in patients with AN, and atrial natriuretic peptide for bulimia nervosa." (PMID 24523928, 2014).
catalepsy (3 papers, 2015 to 2022). A nervous system disorder characterized by diminished responsiveness and consciousness, and rigidity of the body. "Since D2R blockade induces catalepsy we wondered whether Drd2 ablation or D2R antagonism alters behavioral responding (latency to press in the task), an indicator of motivated behavior." (PMID 35856493, 2022).
Headache (3 papers, 2022 to 2025). Cephalgia, or pain sensed in various parts of the head, not confined to the area of distribution of any nerve. "One study reported that the nausea and vomiting experienced by women with hyperemesis gravidarum share a common mechanism with migraine headaches, possibly based on allelic variations within the dopaminergic receptor (DRD2) gene associated with olfaction." (PMID 41010291, 2025).
Lewy body dementia (3 papers, 2021 to 2024). A progressive form of dementia characterized by the presence of protein deposits called Lewy bodies in the midbrain and cerebral cortex, and loss of cholinergic and dopaminergic neurons. "DNA methylation rates of DRD2 in leukocytes were found to be reduced in PD patients but increased in Lewy body dementia (DLB) patients." (PMID 35203939, 2022).
liver cancer (3 papers, 2022 to 2023). An epithelial or non-epithelial malignant neoplasm that arises from the liver. "Similarly, fisetin as a DRD2 agonist suppressed liver cancer cell proliferation and reduced EMT through VEGFR1, p-ERK1/2, p38 and pJNK pathways." (PMID 35372029, 2022). "Furthermore, DRD2 agonist could suppress liver cancer cells proliferation, migration and invasion." (PMID 36091153, 2022).
liver fibrosis (3 papers, 2022 to 2024). "Consistent with this, antagonism of DRD2 or myeloid-specific genetic ablation of Drd2 reduced CCl4-induced liver fibrosis." (PMID 35805148, 2022). "Notably, the selective inhibition of YAP in macrophages through Dopamine receptor D2 (DRD2) antagonism has demonstrated promise in preventing liver fibrosis, making it a potential candidate for treating nonalcoholic steatohepatitis (NASH)." (PMID 38090595, 2023). "Similarly, in NASH and bile duct ligation mouse models, DRD2 deletion in macrophages impaired liver fibrosis." (PMID 35805148, 2022).